GPT (glutamic--pyruvic transaminase)
Diseases named in the same sentence as GPT in open-access papers (continued):
Sharing a sentence is not in itself a finding about the gene and the disease.
scrub typhus (11 papers, 2015 to 2025). Scrub typhus is a rare dust mite-borne infectious disease caused by the Orientia tsutsugamushi bacterium and characterized clinically by an eruptive fever which is potentially serious. "Fifty percent of scrub typhus patients had low platelet count and >30% of patients had an elevated level of liver enzymes (such as serum glutamic oxaloacetic transaminase (SGPT) and serum glutamic pyruvic transaminase (SGOT)." (PMID 34068402, 2021).
delirium (10 papers, 2020 to 2025). A disorder characterized by confusion; inattentiveness; disorientation; illusions; hallucinations; agitation; and in some instances autonomic nervous system overactivity. "Several trials reported adverse effects in the acyclovir arm such as rise in hepatic transaminases Serum glutamic oxaloacetic transaminase (SGOT) and Serum glutamic pyruvic transaminase (SGPT), rash, nephrotoxicity and delirium." (PMID 33265920, 2020).
schizophrenia (10 papers, 2011 to 2025). A major psychotic disorder characterized by abnormalities in the perception or expression of reality. "Coriobacteriaceae has been shown to be associated with impairment of liver function owing to air pollution in patients with schizophrenia, with the main pathways being “NO2/Coriobacteriales/GGT” and “NO2/Coriobacteriales/GPT” pathways." (PMID 37050898, 2023).
cardiac hypertrophy (8 papers, 2014 to 2026). "Lab tests revealed elevated creatine kinase and glutamic-pyruvic transaminase levels, and an ultrasound cardiogram showed ventricular hypertrophy, suggesting neonatal jaundice, liver dysfunction, and potential hypertrophic cardiomyopathy." (PMID 38778310, 2024).
hypersplenism (8 papers, 2011 to 2025). Overactive functioning of the spleen, resulting in excessive destruction of blood cells. "The course of the mean values of the laboratory markers for liver function (GOT, GPT, GGT, bilirubin) and hypersplenism (platelet counts) were similar in the intervention group and the control group during long-term f/u." (PMID 41389160, 2025).
non-small cell lung carcinoma (8 papers, 2018 to 2025). A group of at least three distinct histological types of lung cancer, including non-small cell squamous cell carcinoma, adenocarcinoma, and large cell carcinoma. "In consequence, the genes whose products were subunits of multiprotein complexes had a different effect in MSPT compared to +GPT (RIG-I-like receptor signalling pathway and Non-small cell lung cancer pathway)." (PMID 29370226, 2018).
myelodysplastic syndrome (7 papers, 2020 to 2024). A clonal hematopoietic disorder characterized by dysplasia and ineffective hematopoiesis in one or more of the hematopoietic cell lines. "The increases in GOT and GPT were not significantly different in the myelodysplastic syndrome, chronic myelomonocytic leukemia and acute myeloid leukemia subgroups." (PMID 35626063, 2022).
sarcoidosis (5 papers, 2014 to 2025). Sarcoidosis is a multisystemic disorder of unknown cause characterized by the formation of immune granulomas in involved organs. "IPF and sarcoidosis patients showed differences in CRP (p = 0.01), Hb (p = 0.01), HCT (p = 0.02), WBC (p < 0.001), PLT (p = 0.02), creatinine (p = 0.02) and GPT (p = 0.03) values." (PMID 33089426, 2020).
thyroid cancer (5 papers, 2021 to 2024). "Glutamine metabolism-related genes, including amino acid transporter (ASCT2), amino-releasing enzymes (GLS and GDH), and aminotransferases (GPT, GOT, and PSAT1), were all up-regulated in thyroid cancer cells." (PMID 38386265, 2024). "Other glutamine metabolism-related genes, such as solute carrier family 1 neutral amino acid transporter member 5 (SLC1A5, also known as ASCT2), phosphoserine aminotransferase 1 (PAST1), GPT, and glutamic-oxaloacetic transaminase (GOT), were also highly expressed in thyroid cancer cells." (PMID 38386265, 2024).
coccidiosis (4 papers, 2018 to 2025). A parasitic infection caused by Coccidia. "None of the serum parameters, including total cholesterol, triglycerides, glutamic-oxaloacetic transaminase, glutamic-pyruvic transaminase, uric acid, and nitric oxide, were affected by coccidiosis vaccine challenge or dietary treatments." (PMID 32183035, 2020). "As to serum parameters, coccidiosis challenge or dietary EEO treatments did not affect any of the parameters, including total cholesterol, triglycerides, glutamic-oxaloacetic transaminase, glutamic-pyruvic transaminase, uric acid, and nitric oxide in serum samples." (PMID 32183035, 2020).
gastric adenocarcinoma (4 papers, 2016 to 2021). "The authors also reported a slight excess of SNVs from TpT to GpT, resembling esophageal and gastric adenocarcinomas." (PMID 29416670, 2018).
glioblastoma (4 papers, 2023 to 2025). The most malignant astrocytic tumor (WHO grade IV). "Another transaminase, glutamate pyruvate transaminase (GPT, also known as alanine aminotransferase), responsible for the reversible conversion of glutamate into α-KG, requires HIF2, but not HIF1, for expression in human glioblastoma cells." (PMID 36644500, 2023).
adenoma (3 papers, 2024 to 2025). A neoplasm arising from the epithelium. "Several enzymes involved in NEAA biosynthesis were significantly regulated (highlighted in bold) in late-stage adenocarcinoma cells (M) in comparison to early adenoma cells (C1), such as upregulation of GPT and GLS2, and downregulation of GOT2 and GPT2." (PMID 39332495, 2024). "When the colonic mucosa transforms into an adenoma, the sponging by OIP5-AS1 shifts to miRNA-335 promoting the expression of GPT, which catalyzes pyruvate to alanine by transamination." (PMID 38773399, 2024).
Intellectual disability (3 papers, 2023 to 2025). "GPT variants disrupt neurotransmitter release, causing generalized CNS dysfunction, significant intellectual disability in patients, and MRI findings of abnormal myelin formation in subcortical white matter." (PMID 40547214, 2025). "GPT variants interfere with synaptic neurotransmitter release, leading to generalized CNS dysfunction, with patients presenting significant intellectual disability and MRI showing subtle incomplete and abnormal myelin formation involving subcortical WM." (PMID 39273172, 2024).
Lewis lung carcinoma (3 papers, 2021 to 2024). "Few studies have investigated pharmacological strategies for targeting alanine metabolism, yet l-cycloserine has been identified as an inhibitor of ALT/GPT that can attenuate the in vitro and in vivo growth of LLC1 Lewis lung carcinoma cells." (PMID 34277440, 2021).
tauopathy (3 papers, 2022 to 2024). Neurodegenerative disorders involving deposition of abnormal tau protein isoforms (tau proteins) in neurons and glial cells in the brain. "Notice that this is consistent with PSP, GGT, GPT, AGD and CBD being 4R tauopathies, that distinguishes them from AD and CTE which are 3R+4R tauopathies." (PMID 38555402, 2024). "The right handed tauopathies have different tuples and among them CBD and AGD differ by at most one entry, while CBD and AGD differ by at least 2 entries from PSP, GGT and GPT." (PMID 38555402, 2024). "Regarding two-nucleation-core hexameric sequences, VQIVYK is present in all tauopathy structures so far determined; however, VQIINK is only presented in tau filaments structures with the presence of dual-hexamer core sequences (CBD, AGD, PSP, GGT, and GPT)." (PMID 36558893, 2022).
Cerebral atrophy (2 papers, 2022 to 2023). Atrophy (wasting, decrease in size of cells or tissue) affecting the cerebrum. "Similarly, other blood parameters involved in the degree of cerebral atrophy, such as ALP, GPT, γGTP, and GLU, did not significantly exceed normal values." (PMID 35585840, 2022).
primary hyperoxaluria (2 papers, 2013 to 2016). A hereditary disorder characterized by excessive oxalate production, leading to hyperoxaluria. "Besides applications for PH1 therapy, drugs reducing hyperoxaluria by GPT overexpression might be effective also for treatment of other forms of primary hyperoxalurias (e.g., PH2 and PH3) and more common forms of secondary hyperoxaluria." (PMID 27239044, 2016).
sarcoma (2 papers, 2015 to 2022). A usually aggressive malignant neoplasm of the soft tissue or bone. "We analyzed routinely determined laboratory markers including the blood glucose level, CRP, creatinine, uric acid, natrium, and calcium, as well as GGT, GPT, GOT, LDH, and the occurrence of IIN in sarcoma patients." (PMID 36233666, 2022).
advanced heart failure (1 paper, 2022). Patients with advanced heart failure have severe limitations, experiences symptoms even while at rest and are mostly bedbound patients. "Preoperative serum levels of creatinine, glutamic oxaloacetic transaminase (GOT), glutamic pyruvic transaminase (GPT) and bilirubin as signs of secondary end-organ damage due to advanced heart failure, were comparably elevated in both study-groups." (PMID 35216595, 2022).
endometrial cancer (1 paper, 2020). Primary or metastatic malignant neoplasm involving the endometrium (mucous membrane that lines the endometrial cavity). "GPI, GPT, and LPCAT1 were frequently overamplified in endometrial cancer patients, while ADCY9 more often had missense mutations (unknown significance)." (PMID 32894095, 2020).
Hyperoxaluria (1 paper, 2016). Increased excretion of oxalates in the urine. "Hence, we confirmed GPT as a modifier gene or potential drug target for oxalate detoxification in patients with hyperoxalurias either primary or secondary." (PMID 27239044, 2016).
neurotic depression (1 paper, 2024). "The drug PHENELZINE targeted GPT is used for the treatment of atypical, non-endogenous, or neurotic depression." (PMID 39273172, 2024).
tumor (822 papers, 1995 to 2026). "Interestingly, we also found that GPT expression was associated with the tumor microenvironment in CRC through bioinformatics." (PMID 37851339, 2023). "The glucose uptake in tumor tissues as per the PET/CT images was correlated to serum levels of glutamic-pyruvic transaminase (ALT), total bilirubin (TBIL), creatinine (CRE)." (PMID 37475862, 2023). "GPT expression is closely related to the tumor microenvironment and can effectively distinguish the sensitivity of different CRC patients to clinical drugs." (PMID 37851339, 2023). "Multivariate analysis showed that the mRNA expression of LYRM4 was related to ALT (glutamic-pyruvic transaminase), tumour thrombus, and encapsulation of HBV-related LIHC patients (p ˂ 0.05)." (PMID 34488769, 2021). "Furthermore, we sorted the expression of the tumor tissues, we found that GPT had the lowest expression level in TGCT and the highest expression level in LIHC." (PMID 37851339, 2023). "In summary, our systematic analysis of GMRGs screened for GPT as a potential diagnostic and prognostic marker for CRC, revealed the correlation between GPT and the tumor microenvironment, and explored the relationship between GPT expression and sensitivity to common drugs." (PMID 37851339, 2023). "High levels of SGOT (Serum glutamic-oxaloacetic transaminase) and SGPT (Serum glutamic-pyruvic transaminase) suggest that liver and kidney function impairment might be triggered by tumor invasion." (PMID 36558514, 2022). "Our results indicated that both 5-Fu and Brucea javanica oil could decrease the levels of GOT and GPT in H22 tumor-bearing mice in different extent and Brucea javanica oil in dose no more than 1.5 g/kg bw didnot have obvious toxicity to the liver." (PMID 26508976, 2015). "The results suggested that tadalafil capacity of anti-tumor partially depended on pde5 and its effect on amino acid metabolism also depended on pde5, which was presented by the downregulation of the expression of GPT, GGT5, and TAT in tadalafil treatment with pde5 knockdown groups." (PMID 35694253, 2022). "In tumor‐bearing mice, DOX‐induced toxicity was further exacerbated, with significantly higher levels of BUN, CKMB, LDH, GOT, and GPT compared to sham controls." (PMID 41306344, 2025). "Then, we utilized bioinformatics to analyze the biological role of GPT in CRC and explore the relationship between its expression and tumor microenvironment (TME) and drug sensitivity." (PMID 37851339, 2023). "As expected, the tumor had a significant intoxication effect as observed in elevated levels of LDH, MDA, NO, GOT and GPT in the EAC‐bearing positive group compared to normal levels in the negative controlled group." (PMID 36308603, 2022). "The vaccine somewhat restored the deterioration of the biochemical parameters (LDH, GOT, GPT, MDA, NO, and PON-1) in the tumor-bearing mice." (PMID 36308603, 2022). "Consistent with the in vitro observations, BBR treatment significantly reduced GPT activity levels in orthotopic tumor tissue, while this effect was reversed in BBR-treated HCC tumor tissue with GPT1 overexpression." (PMID 32660149, 2020). "The number of tumours on the surface of the liver was counted 14 days following the start of the infusion, and the serum glutamic-oxaloacetic transamine (GOT), glutamic-pyruvic transaminase (GPT) and total bilirubin concentrations were examined." (PMID 7545415, 1995). "The key laboratory values assessed during this phase include alkaline phosphatase (AP), glutamate oxaloacetate transaminase (GOT), glutamate–pyruvate transaminase (GPT), gamma-glutamyl transferase (GGT), albumin, total bilirubin, and tumor markers CA 19-9, CEA, and AFP (alpha-fetoprotein)." (PMID 39796681, 2024). "It was reported that the levels of GOT and GPT in serum would increase significantly when H22 cells were implanted into mice, and cytoxan (CTX) could decrease the levels in H22 tumor-bearing mice." (PMID 26508976, 2015).
tumor (continued). "We did not notice any correlation of AST/GOT and ALT/GPT with tumor sizes." (PMID 27659353, 2016). "RCE plus Oxa did not change GOT, GPT, UREA, and CREA levels in humanized PD-1/PD-L1 MC38 tumor mice serum." (PMID 36139451, 2022).
infection (788 papers, 2004 to 2026). The state of being infected such as from the introduction of a foreign agent such as serum, vaccine, antigenic substance or organism. "The flanking region 5′ of this fragment harbors a gene coding for a phage tail length tape measure protein (GpT), which is known to dictate the tail length and facilitate DNA transit to the cell cytoplasm during infection." (PMID 36422324, 2022). "In patients with infection-triggered onset we observed strong intercorrelations between markers of organ function and damage GPT, GOT, GGT, LDH and CK as well as AAB." (PMID 33889154, 2021). "In concordance with temporary disease, GPT levels significantly increased in CD4+ T cell recipients until day 14 post infection, reaching comparable levels as in infected control mice." (PMID 28222146, 2017). "Comparing groups N and Tc, it was observed that infection by T. cruzi led to a significant increase in the four markers: 4.0× for GPT, 8.8× for GOT, 1.3× for urea and 3.6× for CK." (PMID 19213854, 2011). "In addition, GPT levels were detected in the serum during the course of infection as a measure for liver damage that is observed in CB17 SCID mice upon R. typhi infection." (PMID 28222146, 2017). "Dialysis-related infection detection uses WBC count, glutamic oxaloacetic transaminase (GOT), glutamic pyruvic transaminase (GPT), alkaline phosphatase, and ferritin levels." (PMID 38673554, 2024). "After infection with Leptospira, both alkaline phosphatase (ALKP) and glutamic pyruvic transaminase (GPT) continued to increase." (PMID 35192629, 2022). "Liver transaminases GPT and GOT were significantly higher at HEV infection compared to the time before and after infection, respectively." (PMID 36514177, 2022). "Blood samples at three time points (before the infection, and on the 11th and 20th days after infection) were analyzed for differential WBC counts and biochemical (ALT/GPT, AST/GOT, and total protein) parameters." (PMID 34680839, 2021). "When Epi-1 was supplied as a curative agent 30 min post-infection, MRSA-induced abnormalities in blood uric acid (UA), blood urea nitrogen (BUN), creatine (CRE), GOT, and GPT levels were restored to normal levels." (PMID 31835381, 2019). "Because CB17 SCID mice develop severe liver necrosis upon R. typhi infection, we also assessed serum GPT levels as a measure for liver damage in all groups of mice at the time of death and in surviving CD4+IFNγ-/- T cell recipients at day 34 post infection when the experiment was terminated." (PMID 28222146, 2017). "In our group, GPT was over normal (normal ranges 10–37 U/L) found in 32/41 (78,04%) patients, out of whom 21/32 (65,62%) had HCV infection, 10/32 (31,25%) HBV infection and 1/32 (3,12%) patients double infection HBV+HCV." (PMID 20945824, 2010). "In our study, plasma GPT and GOT activities were significantly increased to the highest levels at 24 h after A. hydrophila infection and decreased gradually at the later infective stages, indicating that A. hydrophila infection led to severe hepatic damage at the initial stage of infection." (PMID 38799475, 2024). "Hence, methods to attenuate BUN, CRE, UA, GPT, and GOT increases in blood following infection may prevent mortality as well." (PMID 31835381, 2019). "GPT levels in CD4+IFNγ-/- T cell recipients including those that succumbed to the infection were generally normal, whether treated with isotype antibody or anti-TNFα, while serum GPT was enhanced in control animals compared to non-infected mice." (PMID 28222146, 2017). "In line with the trTregs and ILC2 responses, early infection in IL-33-treated mice progressed with a tendency toward reduced GOT and CPK levels, with no changes in LDH and GPT activity, or glucose concentrations." (PMID 39883714, 2025).